CD4 (CD4 molecule)
Diseases named in the same sentence as CD4 in open-access papers (continued):
Sharing a sentence is not in itself a finding about the gene and the disease.
colorectal cancer (continued). "Exosomes secreted by colorectal cancer (CRC) cells deliver lncRNA CRNDE‐h to CD4+ T cells to upregulate the excretion of IL‐17 to induce the differentiation from naive CD4+ T cells into Th17 cells." (PMID 38585234, 2024). "IL-2 treatment of colorectal cancer patients in a phase I/II peptide vaccination trial observed an expansion of peripheral CD4+CD25highFOXP3+ Treg cells." (PMID 39232704, 2024). "In colorectal cancer, IL-22-producing infiltrating CD4+ and CD8+ T-cells were correlated with a better clinical outcome and increased infiltration of neutrophils, which in turn enhanced anti-tumor T-cell responses." (PMID 39372944, 2024). "Median CD8+ and CD4+ cell densities were higher in our cohort than those reported in colorectal cancer." (PMID 39602457, 2024). "The most overrepresented cell type in colorectal cancer patients compared to healthy individuals was intestinal CD4+ α/β T cells (p < 10−6, fold change = 2.1)." (PMID 38472221, 2024). "In colorectal cancer, the proportion of primary tumors with high infiltrates of CD4 and CD8 T cells, particularly in the tumor core, is lower in patients with recurrent tumors." (PMID 39329753, 2024). "In colorectal cancer, B cells, CD4 T cells, CD8 T cells are upregulated, and epithelial cells are downregulated." (PMID 39120585, 2024). "Colorectal cancer patients exhibit a decrease in peripheral CD4+ and CD8+ naive T cells(CD45RAhigh, CCR7high)." (PMID 38735538, 2024). "The over‐abundance of P. micra was linked in the last years with colorectal carcinomas showing a high infiltration degree of immune cells such as CD8+ cytotoxic T, CD4+ T helper and NK cells lymphocytes." (PMID 37558206, 2024). "Colorectal cancer samples also exhibited increased infiltration of mast cells activated, neutrophils, NK cell resting, T cells CD4 memory activated, and T cells follicular helper." (PMID 37304867, 2023). "Overall, we did not observe significant immunologic responses based on the pre-specified primary endpoint of an increase of the percentage of CD8+ TILs and/or the ratio of CD8+/CD4+ TILs in colorectal cancer tissue." (PMID 37120591, 2023). "In CRC, the impact of infiltrating cytotoxic CD8+ and Th1 CD4+ T lymphocytes within the TME on containing the growth of established colorectal cancer and limiting metastasis is well documented." (PMID 37426665, 2023). "CD4+ T cells polarize into different subsets: the main subsets in colorectal cancer are Th1, Th2, Th17, Th22, induced or natural regulatory T cells (iTregs and nTregs) and follicular helper cells (Tfh cells)." (PMID 37511431, 2023). "Further, PDL1 inhibition induces the expansion of CD4/CD8 T cells expressing ICOS molecules in the tumor microenvironment of colorectal cancer patients." (PMID 37261362, 2023). "The high expression of ICOSLG on CD4+ T cells is positively correlated with advanced TNM stage in colorectal cancer (CRC)." (PMID 37842091, 2023). "Circulating miR-221/222 reduced the number of peripheral CD4+ T cells by inhibiting CD4 expression in colorectal cancer." (PMID 37928434, 2023). "For example, infiltration of activated CD4+ memory T cells was noticeably higher in colorectal cancer tissues compared to normal tissues." (PMID 38090588, 2023). "The Tr1-like cytotoxic CD4 T cells in colorectal cancer were suggested to differentiate from Th1-like cytotoxic CD4 T cells in the tumor." (PMID 37654482, 2023). "Through targeted down-regulation of miR-144-3p, it induced CD4+ T cell apoptosis and activated PD-1/PD-L1, which mediated the immune escape of colorectal cancer." (PMID 36092924, 2022). "It has been found that IL22-producing CD4+ T cells promote colorectal cancer stemness which enhance tumorigenesis." (PMID 35874683, 2022).
colorectal cancer (continued). "(D), (E) FCM determination demonstrated that colorectal cancer patients with positive VPS9D1-AS1 expression had lower levels of IFNAR1 in CD4+ and higher levels of PD1 in CD8+ T cells in peripheral blood than these patients with negative VPS9D1-AS1 expression." (PMID 36458816, 2022). "In colorectal cancer, the source of IL-22BP was determined to consist of DCs, CD4+ T cells, and eosinophils." (PMID 36551508, 2022). "HIV-infected colorectal cancer (CRC) patients had similar tumor-infiltrating lymphocytes (CD4 and CD8 T cells) compared to HIV-uninfected controls and significantly similar PD-1 expression on TILs and tumor PD-L1 expression." (PMID 35311077, 2022). "This is consistent with the results of a previous study; the analysis with global gene expression profiling of human colorectal cancer cell lines showed that the expression of SLC2A3 was positively correlated with CD4+ and CD8+ T cells." (PMID 35957685, 2022). "We analyzed the immune cell infiltrates of head and neck squamous cell carcinoma and colorectal cancers and identified a subset of CD4+ Th cells distinct from FOXP3+ Tregs that coexpressed programmed cell death 1 (PD-1) and ICOS." (PMID 35439168, 2022). "As suggested in colorectal cancer, C1Q+ macrophages tend to be dominant in tumors and play roles in recruiting and regulating regulatory CD4+ T cells (Tregs) and exhausted CD8+ T cells, implying the immunosuppressive function of C1Qs+ macrophages." (PMID 35982235, 2022). "Colorectal carcinoma patients presented with significantly lower values of absolute circulating B cell, T cell (CD4 + and CD8 +) and NK cell counts including various subsets compared to healthy volunteers in univariate analysis." (PMID 34928423, 2022). "There were significantly more infiltrating dendritic cells activated, mast cells activated, monocytes, and T cells CD4 memory resting in colorectal cancers with C3 lower expression compared to those with higher C3 expression (all p-values < 0.001)." (PMID 34722636, 2021). "Treg cells with satisfactory phenotype and function were successfully expanded from CD4+CD25+ cells in patients with colorectal cancer." (PMID 33868236, 2021). "The expression of activated memory CD4+ T cells, M0 macrophages, and M1 macrophages in colorectal cancer was higher than that in normal tissues." (PMID 33816234, 2021). "To identify drivers of resistance to anti-PD-1 immunotherapy during MC-38-induced colorectal cancer, we analyzed CD4+ and CD8+ T cell populations within the tumor tissue by utilizing flow cytometry." (PMID 34771497, 2021). "For example, in colorectal cancer, higher CD8/CD4 ratios are associated with longer disease-free survival." (PMID 34433433, 2021). "Conversely, a high density of infiltrating CD4+ T cells indicates improved relapse-free survival and disease-specific survival in colorectal cancer patients." (PMID 33968780, 2021). "Expression levels of CD4+ T lymphocyte subsets in peripheral blood in the colorectal cancer, benign tumor, and healthy control groups." (PMID 34327142, 2021). "Recent evidence outlines the role of CD4+T cells in colorectal cancer responses and suggests possible mechanisms driving qualitative alterations in anti-cancer immune responses." (PMID 34489941, 2021). "Upregulation of IL-10 transcription through MEK/ERK/AP-1 pathway was shown in KRAS mutant colorectal cancer cells and its secretion was required for the conversion of CD4+ T cell to CD4+FoxP3+ Treg cells." (PMID 33777798, 2021).
colorectal cancer (continued). "In other types of cancers, like colorectal cancer, CD4+CD25+FOXP3+ Tregs are extensively increased in tumors in correlation with their stages." (PMID 34055618, 2021). "Previous studies have confirmed that CD4+ GzmB+ T cells were involved in the antitumor immune response of bladder cancer, non-small cell lung cancer, and colorectal cancer." (PMID 34631551, 2021). "It is reported that in a colorectal cancer study that Naïve Tregs (CD3+CD4+FOXP3lowCD45RA+) and effector Tregs (CD3+CD4+OXP3highCD45RA−) have immunosuppressive activity whereas non-Tregs (CD3+CD4+FOXP3lowCD45RA−) have antitumour activity." (PMID 34150643, 2021). "The absolute value and frequency of CD4+ TSCM can clearly distinguish colorectal cancer, benign tumors, and healthy controls." (PMID 34327142, 2021). "We also performed FACS analysis to show that TNFRSF11B decreased the infiltration of central memory CD4+ T cells and effector memory CD4+ T cells in the colorectal cancer microenvironment (all p <0.001)." (PMID 34938284, 2021). "Deregulation in Th1 and Th2 subsets of CD4+ T cells in peripheral blood of colorectal cancer patients has been highlighted in." (PMID 32655551, 2020). "IL-17A-producing CD4+ T (Th17) cells play an important role in the pathogenesis of colorectal cancer." (PMID 32132993, 2020). "A previous study has reported that infiltration of CD4+ lymphocytes is frequent in colorectal cancer." (PMID 32457797, 2020). "Secretion of CXCL10 and CCL5 in the tumor has been associated with accumulation of granzyme producing CD8+ and IFN-γ producing CD4+ T cells in colorectal carcinomas, and early TNM staging." (PMID 32033490, 2020). "For example, increased infiltration of CD8+ and CD4+ T cells was associated with CXCL16 and its receptor CXCR6 expression in colorectal cancers." (PMID 30774761, 2019). "LAG-3+CD4+CD25+ Treg isolated from colorectal cancer patients secrete high levels of immunosuppressive cytokines including TGFβ and IL-10, thereby maintaining the immunosuppressive milieu." (PMID 31681327, 2019). "In an adoptive transfer model, enforced expression of β-catenin in intratumoral CD4+ T cells increased IL-17a expression, enhanced proliferation and inhibited apoptosis of colorectal cancer cells." (PMID 28147310, 2017). "What’s more, it has been revealed that Tregs can hinder CD4+ T cell responses to colorectal cancer antigens, thus contributing to malignant progression." (PMID 29312592, 2017). "Nevertheless, in four of these studies in which double labeling of FoxP3 combined with CD4+, CD25+ or CD8+ was applied, the double-positive T cells were generally associated with a poor prognosis except colorectal cancer." (PMID 26604855, 2015). "Our previous study has revealed that the population of CD4+LAP+ cells was increased in the peripheral blood of colorectal cancer (CRC) patients; moreover, these cells demonstrated a TGF-β–dependent suppressive phenotype." (PMID 25268580, 2014). "In order to investigate the role of LAP in human CD4+Foxp3+ Tregs, we designed a cross-sectional study that involved 42 colorectal cancer (CRC) patients." (PMID 25268580, 2014). "The degree of ThPOK/CD4 colocalization in NM and MA was similar, it was significantly lower in colorectal carcinomas." (PMID 23349906, 2013). "From a clinical standpoint, a high density of tumour-infiltrating CD4+ Th1 cells has been recently shown as a good prognostic marker in colorectal cancer patients emphasizing the role of these cells in cancer immunosurveillance." (PMID 23284752, 2012). "On a cell-to-cell basis highly purified CD4+CD25high Treg cells from colorectal cancer patients (before initiation of therapy) showed an equally strong inhibitory function on conventional CD4+CD25− T-cell proliferation (dark grey bar, p<0.001)." (PMID 22276195, 2012).
colorectal cancer (continued). "Using phenotypic, functional and molecular approaches we demonstrate an increase of CD4+CD25highFOXP3+ Treg cells in colorectal cancer patients already before initiation of an IL-2 containing chemoimmunotherapy regimen." (PMID 22276195, 2012). "Taken together, we demonstrate an in vivo expansion of fully functional CD4+CD25highFOXP3+ Treg cells in colorectal cancer patients due to an increase in naïve Treg cells with an increased TREC content." (PMID 22276195, 2012). "PB derived CD4+ T cells from two colorectal cancer patients and two age-matched healthy individuals were sorted according to their CD25, CCR7 and CD45RA expression into the appropriate CD4+CD25high Treg-cell subsets, namely Tnaïve, TCM, and TEM." (PMID 22276195, 2012). "Our data indicate that an expansion of CD4+CD25highFOXP3+ Treg cells occurred in the majority of colorectal cancer patients after IL-2 administration as part of combined chemoimmunotherapy." (PMID 22276195, 2012). "In conclusion, our data demonstrate the ability of CLA and VSL#3 to ameliorate inflammation-induced colorectal cancer through a mechanism involving modulation of mucosal CD4+ T cell polarization and modulation of gene expression." (PMID 22511958, 2012). "In this study we examined the lymph nodes of Stage II colorectal cancer patients to identify CD4+, CD8+ and Foxp3+ cell populations and correlated these with patient outcome, alone, and in combination with other clinico-pathological variables." (PMID 21864372, 2011). "The CD4/CD8 ratio also has implications as a biomarker in IBD, and their IHC density may also associate with the prognosis of colorectal cancer." (PMID 41149805, 2025). "The abundant recruitment of CD8+ and CD4+ tumor specific T cells in colorectal cancer may contribute to the direct killing of malignant cells." (PMID 40033767, 2025). "Interestingly, subsets of Th1-like CD4 T cells with high expression of Bhlhe40 were previously found to be enriched in patients with microsatellite instability colorectal cancer, who display favorable outcomes in response to anti-CTLA-477." (PMID 38187708, 2024). "MYOSLID knockdown has been reported to lead to a decrease in CD4+ T cells in colorectal cancer cells, which may play a role in regulating immunity to colorectal cancer." (PMID 39355236, 2024). "Extracellular vesicles derived from LGG improved anti-PD-1 immunotherapy efficacy against colorectal cancer by increasing the CD8+ T/CD4+ T cell ratio in mesenteric lymph nodes and enhancing the ratio of MHC II+ DC cells, CD4+ T cells, and CD8+ T cells in tumor tissues." (PMID 39125280, 2024). "Single-cell RNA sequencing and T cell receptor analyses from colorectal cancer biopsies demonstrated that microsatellite-instable tumors (which are more likely to respond to ICIs) showed a preferential enrichment of a Th1-like subset of CD4+ T cells." (PMID 39510069, 2024). "Although CD4 + T cells can polarize into different subsets, which either stimulate or inhibit the immune response to cancer cells, higher levels of CD4 + cell infiltration in tumor tissues were related to better clinical outcomes in colorectal cancer in previous studies." (PMID 38627864, 2024). "Moreover, L. gallinarum-derived ICA suppressed colorectal cancer by inhibiting CD4+ Treg differentiation and enhancing CD8+ T cell function." (PMID 39508089, 2024). "Interestingly in colorectal cancer, cytotoxic CD4 T cells with a Tr1-like phenotype are positively correlated with response to PD1 blockade, which was in direct contrast to their negative association with survival in the absence of PD1 blockade." (PMID 37654482, 2023).
colorectal cancer (continued). "A recent study has demonstrated that resting CD4 memory T cells were the protective factor for CRC (colorectal cancer) and could act as an independent prognostic factor based on a large sample analysis of 879 CRC patients." (PMID 37664030, 2023). "We show an association between HMGB1 expression intensity and density of immune cell subsets in colorectal cancer; nuclear and cytoplasmic HMBG1 associated with increased CD4+ lymphocytes, and nuclear HMGB1 associated with increased FOXP3+ and ICOS+ lymphocytes and reduced CD8+ T-cells." (PMID 36980751, 2023). "The impact of conventional CD4-positive T cells with a T cell receptor consisting of an alpha chain and a beta chain in colorectal cancer is complicated, as T helper cells exist in a great variety of different subsets with both anti-tumoral and pro-tumoral functions." (PMID 37511431, 2023). "This suggests that KCNJ14 and CD4 + T cells may exert a synergistic effect to promote the formation of an inhibitory immune microenvironment in colorectal cancer." (PMID 36100894, 2022). "A high concentration of IL-24 could also downregulate the Treg percentage (i.e., FoxP3 mRNA) and promote CD4+ T cell proliferation in colorectal cancer." (PMID 35752792, 2022). "T cell CD4 memory resting was reported to correlate with poor outcome in colorectal cancer." (PMID 35534879, 2022). "According to the results of the pan-cancer analysis, we found that the abundances of CD4 + T cells and CD8 + T cells were significantly elevated in the mutated ARID1A, mutated ARID1B and mutated ARID2 groups, especially for colorectal cancer and gastric cancer." (PMID 35239432, 2022). "F nucleus might inhibit anti-tumor immune response by reducing the density of CD4+ T cells in colorectal cancer." (PMID 35395711, 2022). "Studies showed that the intratumoral infiltration of CD4 and CD8 T lymphocytes was associated with postoperative recurrence rate and overall survival rate of colorectal cancer patients, and patients with a high infiltration of CD8 T lymphocytes in HCC tissues had a better prognosis." (PMID 35986302, 2022). "It worth to mention that a trial declared that combination of interleukin-6, piRNA, and a kind of micro RNA can lead to the transformation of cancer cells into CD4 + cells and therefore, it can be a useful procedure, in coming years, as combined therapy for colorectal cancer." (PMID 34193172, 2021). "In one notable study, Shimon Sakaguchi’s group showed that CD4+ Tregs isolated from colorectal cancer patients could be subdivided into two functionally distinct populations based on levels of FoxP3 expression." (PMID 32457487, 2021). "The markers of immunoscore in colorectal cancers are CD4- and CD8-positive TILs." (PMID 34898543, 2021). "However, other studies have found the reverse with TBX21-predominant expression specifically in GZMB+ CD4+ T cells in both human colorectal cancer and dengue viral infection." (PMID 34910940, 2021). "Moreover, in colorectal cancer patients, other immune checkpoint inhibitors have been found to be epigenetically regulated in CD4+ and CD8+ tumor infiltrating lymphocytes." (PMID 34262562, 2021). "When analyzing the clinical relevance of tumor-infiltrating T cells, it has been demonstrated that high densities of CD4+ memory T helper (TH) 1 cells and CD8+ T cells are associated with improved disease-free and overall survival (OS) of colorectal cancer patients." (PMID 32194568, 2020). "Thus, high frequencies of CD4+ TH1 cells and CD8+ T cells in the tumor center and the invasive margin were associated with improved OS of colorectal cancer patients." (PMID 32194568, 2020). "The staining intensity score for CD4 was strongest in lung and colorectal cancer cases." (PMID 33437521, 2020).